CDC42 (cell division cycle 42)
Diseases named in the same sentence as CDC42 in open-access papers (continued):
Sharing a sentence is not in itself a finding about the gene and the disease.
cancer (continued). "NSC23766, a Rac-specific inhibitor that does not affect Cdc42 or RhoA, has shown remarkable antitumor effects in multiple cancers 23-25." (PMID 32206120, 2020). "Although Rac1/Cdc42 are recognized as attractive therapeutic targets in cancer, no selective inhibitors have advanced to human use." (PMID 31344967, 2019). "Then we speculate that HMGB1 may induce the expression of RAC1 and CDC42 followed by binding to TLR4, and activate PI3K/AKT signaling pathway, which plays an important role in cancer cell growth and malignant transformation." (PMID 30962261, 2019). "Previous studies have shown that increased CDC42 and ROCK1 expression directly correlates with elevated actomyosin contractility, actin turnover and actin polymerization and eventually facilitate the migration of cancer cells." (PMID 31664083, 2019). "CDC42 expression is increased in multiple human cancers, including CRC, and CDC42 overexpression may also contribute to cancer therapeutic resistance." (PMID 31873828, 2019). "Therefore, we examined CDC42, RAC1, and RHOA as potential target proteins of F806 based on their role in the formation and turnover of actin filaments, as well as cancer invasion and metastasis." (PMID 30327774, 2018). "Most studies evaluating whether CDC42 regulates the polymerization of SEPTs (SEPT2/6/7) have examined mammalian cell lines and cancer cells." (PMID 30189608, 2018). "Thus, while our results support the notion that the Rho GTPase Cdc42 is a central initiator of invadopodia formation, they also suggest that multiple mechanisms for invadopodia induction exist and that these could be used in other contexts, including cancer cell invasion." (PMID 26765257, 2016). "We regarded that CDC42, CFL1 and ADFP might promote the process of HBx-induced the inflammation and cancer in liver cells through dysregulation of cytoskeletal remodeling and lipid metabolism." (PMID 27708241, 2016). "SOD2, CDC42/Rac1, and JNK/c-Jun are all known to be involved in cancer development and migration." (PMID 25402510, 2015). "Although previous studies report that CDC42 and Rac1 can activate JNK and regulate cancer cell migration, our results from current studies demonstrated that JNK could also regulate CDC42 and Rac1 expression and subsequently mediate T24 cell migration." (PMID 25402510, 2015). "Although we did not investigate Rac, Cdc42, and mDia in the present study, Rac1 activity was increased in cancers of the human upper urinary tract and was related to tumor progression in our previous study." (PMID 24908363, 2014). "Additionally, inhibition of Rac1/Cdc42 by AZA1 affected cytoskeletal dynamics and suppressed cancer cell migration." (PMID 24040362, 2013). "To analyze signaling pathways that could mediate the effects of AZA1 mediated Rac1/Cdc42 inhibition, we examined the activity of the downstream effector PAK by evaluating PAK phosphorylation in EGF-stimulated cancer cells following AZA1 treatment." (PMID 24040362, 2013). "p120ctn has been shown to stimulate Rac and/or Cdc42 activity and/or inhibit RhoA activity in cells lacking E-cadherin, including fibroblasts and cancer cell lines." (PMID 20668551, 2010). "We suggest thus that CDC42 inhibition by secramine constitutes a potential anti-cancer treatment, but unfortunately neither CDC42 nor secramine appeared in their respective databases used in this study." (PMID 20015360, 2009).
cancer (continued). "miR-15b exerts its effects in these cancers through various mechanisms, such as the regulation of proliferation, apoptosis, epithelial–mesenchymal transition (EMT), and drug resistance, mediated by the NF-κB, STAT3, AKT/mTORC1, CDC42/PAK1, and β-catenin signalling pathways." (PMID 39456841, 2024). "Interestingly, DNMBP is a guanine exchange factor (GEF) regulating CDC42, strengthening the hypothesis about an important role of EBV miRs in cancer." (PMID 39063079, 2024). "RHO, RAC1, and CDC42 are all members of the RHO GTPase family and are involved in the regulation of cytoskeleton, cell growth, and cell cycle, which may be effective targets against malignant tumor metastasis." (PMID 37202394, 2023). "In addition, an overexpression of CDC42 could also inhibit the degradation of EGFR, inducing an increased level of EGFR, which could lead to cancer progression." (PMID 36936942, 2023). "Even when Rac and Cdc42 are not overexpressed or mutated in cancer, they can be activated by a myriad of oncogenic cell surface receptors and guanine nucleotide exchange factors (GEFs) that exchange the GDP on inactive Rac/Cdc42 for a GTP." (PMID 37397366, 2023). "Therefore, MBQ-167 and MBQ-168 can be used to inhibit Rac/Cdc42 in multiple cancers regardless of the individual oncogenic GEF activity." (PMID 36861094, 2022). "The aim of this study was to identify molecular gene signatures, responsible for cancer initiation, progression, resistances and to treatment, metastasis, and also evaluate the potency of our novel compounds SJ10 as potential target for CCNB1/CDC42/MAPK7/CD44 oncogenic signatures." (PMID 35008426, 2022). "Furthermore, the signaling pathway of PI3K-Akt, pathway in cancer, focal adhesion, Rap1, MAPK, and TGF-β may contribute to Cdc42’s regulation of activin B-induced biological function of ADSCs." (PMID 35690801, 2022). "Specifically, reduced Cdc42 levels lead to decreased F-actin content, which, in turn, frees up LATS1, allowing it to bind to and phosphorylate YAP, thereby inactivating it and reducing its nuclear accumulation, finally leading to attenuated cancer cell proliferation." (PMID 34650666, 2021). "Unlike the polarization of epithelial monolayer where Rac1/Cdc42 pathway functions primarily, our data show that collective polarization of carcinoma cells is predominantly controlled by Golgi apparatus, a disruption of which results in the destruction of collective polarization over a large scale." (PMID 33499191, 2021). "Notably, Cdc42 is known to be activated by VEGF-A signalling in cultured endothelial cells and plays a critical role in actin remodelling in a variety of cell types, including cancer cells." (PMID 32139668, 2020). "While the mechanism of activation of CDC42/RAC1 by RHOG, the MAPK by RAC1, as well as the intersection with the RHOA/ROCK1/2 pathways remain topics for future work, we believe this study sheds the light on RHOG as a potentially promising target for anti-angiogenesis in cancer therapeutics." (PMID 30781697, 2019). "The promotion of cancer cell proliferation may be due to activating the mitogenic signalling by modulating epidermal growth factor receptor (EGFR) activation through Cbl and GTPases Cdc42." (PMID 30621321, 2019). "Known, validated targets for miR137 include the cell cycle regulator Cdc42, estrogen related receptor ERRα/NR3B1, p160 nuclear receptor coactivators and the lysine specific demethylase 1 (KDM1A, LSD1), a transcriptional coregulator which is over-expressed in many cancers [14 and references therein]." (PMID 26461474, 2015). "The fact that miR-29 family members are often not expressed in cancer cells could be crucial for cancer control: miR-29 down-regulates important genes such as CDC42, TCL-1 and MCL-1, which normally confer tumor-suppressing traits." (PMID 23245396, 2012).
cancer (continued). "In addition, we identify PP1/NIPP1 as a novel molecular compass that controls directed cell migration via upregulation of Cdc42 signalling and suggest a way by which PP1/NIPP1 may contribute to the migratory properties of cancer cells." (PMID 22815811, 2012). "Besides RAC/CDC42 GTPase, other families of actin-binding proteins may regulate PI3K in cancer." (PMID 35406424, 2022). "In addition, CDC42, together with cell adhesion molecule CD44, were found to be crucial for the motility of cancer cells as they are highly concentrated in the flectopodia, the actin-based cytoplasmic extensions on the cancer cell membrane that impact the contractile activity of pericytes." (PMID 36119528, 2022). "Thus, unlike the Rac1/Cdc42 signaling pathway functioning in epithelial cells, the disruption of the Golgi apparatus trafficking pathways would significantly disturb the collective cancer cell polarization." (PMID 33499191, 2021). "Additionally, while the described studies specifically identify a requirement for Cdc42 in HRasV12-driven transformation, how Cdc42 might affect transformation resulting from the activation of other Ras proteins (i.e. KRAS and NRAS) commonly activated in human cancers remains to be explored." (PMID 22719838, 2012). "To confirm the GAP function of StarD13, we performed a pull-down assay to investigate the differences in GTP loading of RhoA and Cdc42 in SKOV-3 and Caov-3 cancer cells in the presence or absence of StarD13." (PMID 34958986, 2022). "ARHGAP11A was previously proved to be a GAP specific for Rho, but not for Rac or Cdc42, and ARHGAP11A stimulated cancer cell motility by enhancing Rac activity." (PMID 30545369, 2018). "CACNA2D2 is a tumor suppressor gene in several types of cancer, however its role in CRC or correlation with CDC42 has not been described yet." (PMID 28460460, 2017). "Hence, we investigated the novel hypothesis that cancer cells escape the pro-apoptotic effects of μM TMX by inhibiting c-Cbl activation via the redox/Fyn/c-Cbl (RFC) pathway, and that Cdc42 inhibition will enhance the utility of TMX as a potential treatment for ERα-negative cancer cells." (PMID 23606532, 2013). "In contrast, in HT-29 cancer cells, viability and proliferation were not affected by AZA197 at concentrations that significantly inhibit Cdc42 activity as well as cancer cell migration and invasion." (PMID 24279335, 2013). "Given that CDC42-GTP promotes F-actin polymerization and filopodia formation, facilitating cancer cell migration and survival at distant metastatic sites, we found that Reelin treatment upregulated GTP-CDC42 in control cells, with no change observed in LRP8 knockdown cells." (PMID 40506610, 2025). "However, our findings in two cancer-derived cell lines are at odds with the idea that cathodal polarisation is driven by Cdc42, because treatment of parental HTO cells with the Cdc42 inhibitor, ML141, does not affect cathodal migration." (PMID 22815811, 2012).
tumor (350 papers, 2002 to 2026). "To further elucidate the predictive performance of the CDC42 gene set status, we analyze the tumor intrinsic and tumor extrinsic immune response landscapes associated with its status." (PMID 39791593, 2025). "Rac and Cdc42 are key regulators that promote cell motility and are associated with tumor invasion and metastasis." (PMID 35110666, 2022). "Cdc42 is a small GTPase associated with a variety of human cancers, and it is related to cell cycle progression, migration/invasion, tumor growth, and oncogenic transformation." (PMID 34221974, 2021). "As a regulator of both cell architecture and motility, deregulation of Cdc42 is also linked to tumour metastasis." (PMID 34100887, 2021). "Different factors, which have been described to be upregulated in CRC, are associated with activation of CDC42, as a mechanism promoting tumor progression." (PMID 33406731, 2021). "In agreement, targeting of molecules causing CDC42 repression successfully blocks tumor progression and/or metastasis." (PMID 33406731, 2021). "CDC42 is a member of the Rho family of GTPases, which plays a role in many of the cellular processes that are associated with tumour progression, such as cell migration, proliferation, cytoskeletal control and vesicular trafficking." (PMID 32445177, 2020). "Considering that the GAP domain was reported to inactive Rac1 or Cdc42, which is involved in tumor cell migration and associated with MMPs, we detected the Rac1 and Cdc42 activity and MMP-2/9 expression level upon Porf-2 expression." (PMID 32676454, 2020). "CDC42 has been demonstrated that its deregulation can change normal cell function like cell division; it can cause a tumor." (PMID 32497093, 2020). "Nuclear CDC42 expression was associated with a longer BC-specific survival in all cases (p = 0.025) and in luminal ER-positive tumours (p = 0.011)." (PMID 28451966, 2017). "This analysis demonstrated that Cdc42 loss increased formation of bronchial and bronchiolar epithelial tumors, but decreased Kras-induced tumor formation in alveoli." (PMID 28871124, 2017). "Our results further suggest that Cdc42 loss induces Kras-derived bronchiole tumor formation potentially through disruption of cell polarity and cell-cell contact inhibition." (PMID 28871124, 2017). "Bronchial Cdc42 loss destroys contact inhibition potentially through cell polarity disruption, and results in increased tumor formation." (PMID 28871124, 2017). "Here we find that Cdc42 deficiency inhibits the KrasG12D-induced lung alveoli tumor formation, while conversely promotes bronchiole tumor formation in mice." (PMID 28871124, 2017). "Loss of Cdc42 promoted KRAS-induced Club cell tumor formation, underscoring an important tumor initiation function of polarity loss which was previously considered a by-product of abnormal cell accumulation." (PMID 28871124, 2017). "CDC42 has been implicated in tumor development and progression through the alteration of its different roles in a tissue-specific manner." (PMID 28460460, 2017). "Aberrant Ras/Raf/MEK/ERK or RhoA/cdc42/MLKs/MKK/JNK cascades have been implicated in many types of diseases such as tumor formation and neurodegenerative diseases." (PMID 26734995, 2016). "This is because all studies showing CDC42 as an oncoprotein have been conducted with CDC42-v1 or its mutants and thus CDC42's tumor promoting function can be attributed to this variant." (PMID 26336992, 2015). "Taken together, these results indicate that two CDC42 variants have different effects on tumor cell behavior." (PMID 26336992, 2015). "Over-expression of RhoA, RhoB and Cdc42 in the tumours was found to be associated with the presence of lymph node metastases (P = 0.024, P = 0.004 and P = 0.047, respectively)." (PMID 23420497, 2013). "Taken together, these data suggest that Cdc42, Rac1 and RhoA are all closely associated with the invasion and metastasis of tumor cells through regulating the formation of invadopodia." (PMID 23538840, 2013).
tumor (continued). "In the course of defining the numbers of cells to transplant for our in vivo experiments, we observed that Cdc42 knockdown was associated with a reduction in the number of tumours generated in mice transplanted with fewer cells." (PMID 23606532, 2013). "Given the drastic effects of cdc42 deletion on cell proliferation and anchorage-independent growth, it seems likely that Cdc42 loss would impair the ability of HRasV12 to drive tumor formation." (PMID 22719838, 2012). "While constitutive deletion of cdc42 inhibits tumor formation and subsequent growth, to address the feasibility of targeting Cdc42 for therapeutic intervention in tumors driven by HRasV12 mutation, cdc42 was inducibly deleted in established tumors." (PMID 22719838, 2012). "Tumors were isolated at the completion of the study and tumors arising from Cdc42-proficient cells grew significantly larger than Cdc42-deficient tumors and exhibited general differences in tumor architecture." (PMID 22719838, 2012). "RhoA, Rac1, and Cdc42 have each been implicated in tumor motility and invasion, are downstream effectors of both LPA1 and S1P1, and therefore were candidates for targeting." (PMID 17156449, 2006). "Hyperactive Cdc42 has been implicated in tumor cell invasion due to its effects on the actin cytoskeleton." (PMID 16280046, 2005). "Therefore, we investigated the difference in tumor microenvironment (TME) between CDC42 gene set wild type and mutation tumors." (PMID 39791593, 2025). "Furthermore, CD99 depletion in tumour cells caused redistribution of the actin cytoskeleton and increased activity of the Rho GTPase CDC42, known for its role in actin remodelling and cell migration." (PMID 34374417, 2021). "This indicated that CDC42 expression levels may be associated with tumor immunity and immunotherapy." (PMID 33380242, 2021). "In Ustilago maydis, the causal agent of common smut of corn, RAC1 and Cdc42 are required for tumor formation on maize seedlings." (PMID 33924947, 2021). "Deregulation of Cdc42 is also therefore linked to tumour metastasis." (PMID 34100887, 2021). "The factors causing the reduction in Cdc42 expression in the tumor microenvironment remain unclear, and whether endogenous lipid antigens are involved and contribute to the progression of tumors requires further investigation." (PMID 31160756, 2020). "While the universal role of Cdc42 in establishing and maintaining tissue/cell polarity is critical for normal cell division and is also implicated in tumor suppression, Cdc42 activation has been suggested to contribute to tumor cell invasion and migration as well as cellular aging." (PMID 32656257, 2020). "We then asked how Cdc42 loss promoted the bronchiole tumor formation." (PMID 28871124, 2017). "It interacts with the Rho GTPase Cdc42, and acts as a guanine nucleotide exchange factor; thus, its deficiency might lead to impaired tumor immune surveillance." (PMID 29216821, 2017). "Interestingly, we found an association of CDC42 nuclear expression with special histological tumour types such as lobular and tubular tumours." (PMID 28451966, 2017). "The possible intracellular cues that can direct this Endo180-associated tumor cell plasticity include Cdc42 and Rac1 and the Rho-ROCK-MLC2 pathway, which are activated by the spatiotemporal localization of the Endo180 receptor to the plasma membrane or constitutively recycling endosomes." (PMID 26567111, 2016). "Perturbation of Cdc42, Rac1 and RhoA activity results in the loss of normal physiological function and can be related to the pathological conditions, including cellular transformation, tumor invasion and metastasis." (PMID 23538840, 2013).